SPHK2 (sphingosine kinase 2)
Diseases named in the same sentence as SPHK2 in open-access papers (continued):
Sharing a sentence is not in itself a finding about the gene and the disease.
Headache (1 paper, 2025). Cephalgia, or pain sensed in various parts of the head, not confined to the area of distribution of any nerve. "Similarly, genes identified for headache (e.g., ETFA, GRHPR, MMAB) and facial pain (e.g., FASN, SPHK2) also consistently showed protective trends at both the expression and protein levels." (PMID 40943610, 2025).
HIV-1 infection (1 paper, 2022). The type species of lentivirus and the etiologic agent of acquired immunodeficiency syndrome (AIDS). "As SPHK inhibition, in addition to S1PR modulation with FTY720, hinders HIV-1 cell-to-cell transmission, our results suggest that SPHK1 and SPHK2 are involved in HIV-1 infection of primary CD4 T cells and represent unique targets toward halting HIV-1 infection." (PMID 35412343, 2022).
Hyperinsulinemia (1 paper, 2020). An increased concentration of insulin in the blood. "Interestingly, Sphk2-LKO resulted in increased adiposity and hyperinsulinemia under HFD feeding, suggesting Sphk2-LKO might cause extrahepatic impacts via interorganic communication." (PMID 32917816, 2020). "Under the hyperinsulinemia, FBG levels were not significantly elevated in Sphk2-LKO mice, indicating the mice remained in prediabetic stage during the experimental period." (PMID 32917816, 2020).
hyperlipidemia (1 paper, 2022). "SphK2 deficiency abrogated HFHSD-induced body weight gain, hyperlipidemia, hepatic inflammation and fibrosis, resulting in a tumor-suppressive microenvironment." (PMID 36333295, 2022).
insulinoma (1 paper, 2024). "Glucose increases the S1P content by activating SphK2 in mouse insulinoma MIN6 cells and mouse pancreatic islet cells, whereas SphK2 knockdown reduces glucose-stimulated insulin secretion." (PMID 38256005, 2024).
kidney adenocarcinoma (1 paper, 2021). "ABC294640, an SPHK2 selective inhibitor, downregulated the SK1 and SK2 mRNA expression in A498 kidney adenocarcinoma cells, and this initiated the decrease of S1P levels and increment of ceramide levels." (PMID 34502095, 2021).
kidney injury (1 paper, 2022). Trauma to the kidney. "In contrast to the survival effects of SphK1, SphK2 promotes apoptosis/cell death in various types of oxidant-induced kidney injury." (PMID 35409370, 2022). "Taken together, these lines of evidence suggest that SphK1 promotes survival, while SphK2 has the opposite effect in oxidant-induced kidney injury." (PMID 35409370, 2022). "Further studies are needed to determine whether SphK1 and SphK2 differentially regulate cell proliferation in oxidant-induced kidney injury." (PMID 35409370, 2022). "Currently, it remains unknown whether or not SphK2 can suppress ROS production in oxidant-induced kidney injury." (PMID 35409370, 2022).
lupus (1 paper, 2022). "Furthermore, the expression of SphK2 in peripheral blood mononuclear cells remained unchanged in lupus patients, while serum levels of S1P and dh-S1P were higher in SphK2−/− lupus mice than SphK2+/+ lupus mice." (PMID 35409370, 2022).
lymphoma (1 paper, 2023). A malignant (clonal) proliferation of B- lymphocytes or T- lymphocytes which involves the lymph nodes, bone marrow and/or extranodal sites. "Using a web-based database, Gene Expression Omnibus (GEO), the high throughput gene expression was profiled for SPHK1 and SPHK2 in the lymphomas (DLBCL, FL, and PTCL) and the respective normal controls." (PMID 36600310, 2023).
malaria (1 paper, 2020). Malaria is a serious and sometimes fatal disease caused by a parasite that commonly infects a certain type of mosquito which feeds on humans. "A recent knockout study in Pseudomonas aeruginosa induced lung inflammation revealing the pathogenic role of SPHK2 through epigenetic regulation of gene expression and intracellular S1P generation proposes the possible collusion of SPHK2 in malaria induced ARDS." (PMID 32923406, 2020).
malignant glioma (1 paper, 2021). A grade III or grade IV glioma arising from the central nervous system. "Moreover, NEDD4L mediates the ubiquitination of the tumor oncogene sphingosine kinase 2 (SphK2) and thus suppresses the development of malignant glioma." (PMID 34869021, 2021).
mastocytosis (1 paper, 2018). A clonal myeloproliferative neoplasm characterized by the proliferation and accumulation of neoplastic mast cells in one or multiple organs or organ systems. "Similarly, we found an increase in the expression of SPHK1 and SPHK2 in mastocytosis MC lines (i.e., LAD2 and HMC-1) compared with normal HuMCs, which was variable depending on the donor." (PMID 29643855, 2018).
mesothelioma (1 paper, 2012). A usually malignant and aggressive neoplasm of the mesothelium which is often associated with exposure to asbestos. "We also tested the effects of SphK1 and SphK2 downregulation on generation of S1P in control Met5A and mesothelioma H2691cells." (PMID 23028939, 2012). "We also knocked down protein expression of SphK1 and SphK2 with SphK1 and SphK2 specific siRNA in Met5A and H2691 mesothelioma cell lines." (PMID 23028939, 2012). "It is possible that SphK1 in conjunction with S1P many have a similar role to that of SphK2 in modulating HDACs in mesothelioma, which is currently under investigation." (PMID 23028939, 2012). "Although intracellular generation of S1P is higher in mesothelioma cells, they hardly express SphK2." (PMID 23028939, 2012). "Relative levels SphK1 and SphK2 transcripts normalized to 18S were significantly higher in mesothelioma cells lines (H2691, H2461, H513) compared to Met5A." (PMID 23028939, 2012). "In contrast, despite the elevated levels of Sphk2 transcripts, the protein levels were, however, much lower in mesothelioma cell lines compared to of Met5A." (PMID 23028939, 2012). "The endogenous role of SphKs on control (Met5A) and mesothelioma (H2691 and H2461) cell proliferation was investigated using a commercially available inhibitor of SphK1 and SphK2, namely SphK-I2." (PMID 23028939, 2012). "In contrast to the protein expression, mRNA levels of both SphK1 and SphK2 were higher in mesothelioma cell lines compared to control Met5A." (PMID 23028939, 2012). "In the present study, we demonstrate a definitive role for SphK1, but not SphK2, in supporting the proliferation of mesothelioma cells." (PMID 23028939, 2012). "In this study, we have demonstrated for the first time, relatively higher protein expression of SphK1, but not SphK2, in mesothelioma cell lines." (PMID 23028939, 2012). "Met5A and mesothelioma cell lines were labeled with [32P]orthophosphate, and cultured in media containing 1% FBS in the presence or absence of exogenous sphingosine, the substrate for SphK1 and SphK2." (PMID 23028939, 2012). "Our results indicated that SphK1, but not SphK2, regulates mesothelioma cell proliferation through histone acetylation signal transduction." (PMID 23028939, 2012). "Using SphK inhibitor and specific siRNA targeting either SphK1 or SphK2, we also unequivocally established that SphK1, but not SphK2, promotes H2691 mesothelioma cell proliferation." (PMID 23028939, 2012). "The mRNA and protein expression profiles of SphK1 and SphK2 were examined in one control (Met5A, non-malignant transformed mesothelioma cells) and three mesothelioma cell lines using real time RT-PCR and immunoblotting with anti-SphK1 and anti-SphK2 polyclonal antibodies." (PMID 23028939, 2012). "However, our results do not exclude the involvement of SphK2 in mesothelioma and further studies are necessary to understand whether both isoforms play a role in mesothelioma." (PMID 23028939, 2012).
myocardial infarction (1 paper, 2021). Gross necrosis of the myocardium, as a result of interruption of the blood supply to the area, as in coronary thrombosis. "In a pathological setting of myocardial infarction, the bioactive peptide apelin enhances the secretion of S1P in lymphatic endothelial cells, by modulating the expression of Spns2 and SphK2." (PMID 34572307, 2021).
nephrosis (1 paper, 2021). Pathological processes of the KIDNEY without inflammatory or neoplastic components. "SphK2 as well as the activated, phosphorylated form of SphK2 were shown to increase in CD4+ T cells during LCMV Cl 13 infection, and deletion of SphK2 led to increased virus-specific T cell responses resulting in immunopathologic fatality of infected mice with nephrosis." (PMID 34696381, 2021).
neural tube defect (1 paper, 2014). A congenital defect characterized by failure of the neural tube to close completely; this results in the presence of openings in the brain or spinal cord. "We examined the incidence of neural tube defects and weight changes of fetus and placenta, as well as the gene expression of LASS5 (in maternal liver and fetus), Sphk1, Sphk2, Sgpl1, and Sgpp1 in the maternal liver, uterus, fetus, and placenta." (PMID 25383881, 2014).
oral squamous cell carcinoma (1 paper, 2022). "The frequency of immunoreactivity score (IRS) of sphingosine kinase 1 (SphK1) and sphingosine kinase 2 (SphK2) has been calculated with different clinicopathological attributes of oral squamous cell carcinoma patients." (PMID 35494957, 2022).
synovitis (1 paper, 2018). Inflammation of a synovial membrane. "Genes such as NRAS, SPHK2, FOS, CXCR4, PLD1, GNAI2, and PLA2G4F were strongly implicated in synovitis of OA." (PMID 29968759, 2018).
Thrombocytopenia (1 paper, 2024). A reduction in the number of circulating thrombocytes. "Investigations of the development of thrombocytopenia based on blood cell analysis contradicted the development of this part of the HUS triad in WT, SphK1−/−, and SphK2−/− mice with experimental HUS in this study at first glance." (PMID 39062926, 2024).
type 1 diabetes (1 paper, 2018). "For six genes (ORMDL3, GALC, SPHK2, SLC1A5, PPARD and B4GALT1) the SNPs with the strongest association with type 1 diabetes (lowest p value) also acted as cis-eQTLs, suggesting that these SNPs regulate the expression of their associated genes." (PMID 29671030, 2018). "Next, we discovered eight gene polymorphisms (ORMDL3, SPHK2, B4GALNT1, SLC1A5, GALC, PPARD, PPARG and B4GALT1) involved in sphingolipid metabolism that contribute to the genetic predisposition to type 1 diabetes." (PMID 29671030, 2018).
vitiligo (1 paper, 2025). Generalized well circumscribed patches of leukoderma that are generally distributed over symmetric body locations and is due to autoimmune destruction of melanocytes. "We identified seven proteins (HEPHL1, PRDX1, DEFA1, CSGALNACT2, HERC4, NDC80, and SPHK2) causally associated with vitiligo risk." (PMID 40856249, 2025). "Dysregulation of SPHK2 may exacerbate these inflammatory processes, contributing to melanocyte destruction in vitiligo." (PMID 40856249, 2025).
cancer (90 papers, 2010 to 2026). A tumor composed of atypical neoplastic, often pleomorphic cells that invade other tissues. "Recently, it has been demonstrated that high levels of SphK2 are directly associated with aggressive hepatocellular carcinoma differentiation and more frequent cancer recurrence in males." (PMID 39940821, 2025). "SphK1 is more prominently implicated in cancer progression and chemoresistance, while SphK2, although involved in cell death and survival pathways, appears to function differently depending on the cellular context." (PMID 40427516, 2025). "The anti-cancer effects of SphK2 deficiency have been demonstrated in HCC cell lines and xenograft models." (PMID 36333295, 2022). "Two distinct SPHK isoforms, namely SPHK1 and SPHK2, have been identified to date, and the former has been implicated for its oncogenic roles in cancer development and progression." (PMID 34820423, 2021). "SPHK2-deficient cancer cells and fibroblasts exhibit reduced proliferation and express senescence markers." (PMID 34055895, 2021). "We thus suggest that SphK2-induced degradation of RXRα is linked to resistance of cancer cells to ATRA therapy." (PMID 28465486, 2017). "Our study highlights the association between SphK2 and abnormal modulation of RXRα/RARβ in cancer cells." (PMID 28465486, 2017). "On the other hand in cancer associated with inflammation in contrast to oncogenic SphK1, either overexpression or down-regulation of SphK2 has been shown to inhibit cell growth and promote apoptosis in a cell-dependent manner." (PMID 29216917, 2017). "SphK2 inhibition alleviated disorders associated with immunosuppression, such as chronic infections and/or cancers." (PMID 27129720, 2016). "SPHK2 is associated with tumorigenesis, cancer progression, and chemoresistance." (PMID 39678510, 2024). "To further explicate whether the anti-cancer effects of SphK2 deficiency could be attributed to a combinational effect of both SM and ceramide changes, we overexpressed CERT in Huh7 cells prior to FFA treatment." (PMID 36333295, 2022). "Abnormal SPHK2 localization to the plasma membrane is linked to cancer." (PMID 34055895, 2021). "It is important to mention that while upregulation of SphK2 in the nucleus may cause cancer to progress, SphK2 in the mitochondria has the opposite effect." (PMID 33758708, 2021). "Thus, ABC294640 is cytotoxic to the tested primary cancer cells, and its activity is negatively associated with SphK2 expression level." (PMID 26337959, 2015). "We next examined whether SphK2 deficiency led to anti-cancer effects in hepatocytes." (PMID 36333295, 2022). "In summary, by controlling S1P production, SphK1 and SphK2 tune oncogenic signaling networks; their sustained over-expression fuels the initiation and progression of multiple human cancers." (PMID 41234914, 2025). "All together, these data demonstrate a crucial relationship between the modulation of S1P metabolism and drug resistance in human cancer cells while indicating that further studies are needed to target SphK2 in the treatment of cancer." (PMID 39940821, 2025). "The selective SphK2 inhibitor ABC294640 decreases cancer cell growth in vitro and in mouse models of cancer, even though this inhibitor has also been linked to off-target anti-estrogenic effects." (PMID 39940821, 2025). "SPHK-2 activation promotes the proliferation of cancer cells and the progression of inflammation, and SPHK-2 is a key target in the treatment of cancers." (PMID 38965120, 2024). "Evidence from preclinical models of cancer indicates that cancer cells can enhance SPHK2 expression as a survival mechanism in response to ER stress." (PMID 39519028, 2024). "SG12 induces phosphorylation of SphK2 resulting in inhibition and subsequent triggered apoptosis in the cancer cell line." (PMID 38419070, 2024).
cancer (continued). "The SPHK2-specific inhibitor opaganib showed high efficacy in several preclinical cancer models and synergistic anticancer activity with chemotherapies or molecularly targeted therapies." (PMID 38473407, 2024). "Through in-depth research, experts have established that SPHK-2 plays a key role in the pathogenesis and development of cancers." (PMID 38965120, 2024). "Higher S1P levels have been detected in many types of cancer, and are possibly correlated with SphK2 overexpression." (PMID 36982369, 2023). "It is well known that SphK2 is located in both cytosol and nuclei, while cytosolic SphK2 is related to proliferation and cancer, and nuclear SphK2 is involved in gene expression and telomere integrity." (PMID 35897658, 2022). "While elevated SphK2 has contrasting roles in cancers of different types, as discussed in detail below in section 7, inhibition of SphK2 synergizes with PI drugs to kill MM cells and can re-sensitize resistance MM cells." (PMID 35756630, 2022). "In summary, the current study provides both in vivo and in vitro evidence demonstrating a pro-cancer role of SphK2 in the development of NAFLD-HCC." (PMID 36333295, 2022). "Collectively, these data suggest that both SPHK1 and SPHK2 play crucial roles in stimulating tumor growth and survival, supporting the importance of regulating S1P generation for cancer treatment." (PMID 35565311, 2022). "Considering that SphK1 and SphK2 are both important therapeutic targets of NSCLC and SKI-349 is a potent SphK1/2 dual inhibitor, the current study explored the potential anti-cancer activity and the possible underlying mechanisms of SKI-349 in NSCLC cells." (PMID 35831279, 2022). "Mechanistically, SphK2 deficiency led to downregulation of ceramide transfer protein (CERT) that, in turn, decreased the ratio of pro-cancer sphingomyelin (SM) to anti-cancer ceramide." (PMID 36333295, 2022). "Drugs specifically targeting sphingolipid metabolism are mostly in pre-clinical development in cancer, but a specific inhibitor of sphingosine kinase 2, Opaganib (ABC294640), has been tested in patients with solid tumours." (PMID 35331214, 2022). "We observed significant differential expression of SPHK1 in multiple cancers compared with that of SPHK2, which suggested the global ubiquity of SPHK1 dysregulation in cancers." (PMID 36050478, 2022). "In cancer cells, SPHK2 associates with HDAC1 and HDAC2 in the transcription repressor complex, and S1P generated by SPHK2 binds to and inhibits HDAC1 and HDAC2, resulting in epigenetic regulation of gene expression." (PMID 34055895, 2021). "Various SPHK2 inhibitors are being developed to treat cancer, including SPHK2-specific sphingosine‐competitive small molecules." (PMID 34055895, 2021). "The finding that low-level of SphK2 overexpression is able to induce neoplastic transformation in vitro and promote tumorigenesis in vivo sheds a new light on the role of SphK2 in cancer pathogenesis." (PMID 32456134, 2020). "The two isoforms of SphK, SphK1 and SphK2, are involved in regulating physiological and pathological processes, including cancer progression." (PMID 32796926, 2020). "Both SPHK isoforms, SPHK1 and SPHK2, are reported to be involved in regulating oncogenesis in human cancers." (PMID 32260399, 2020). "Sphingosine kinases remain targets of interest for cancer therapy, and inhibitors of both SphK1 and SphK2 have been investigated in clinical trials." (PMID 32521763, 2020). "In contrast to the well-studied oncogenic roles of SphK1 in cancer progression, the roles of SphK2 remain controversial for both pro-apoptotic and pro-survival functions have been suggested." (PMID 32796926, 2020). "Pharmacological inhibition of SphK2 activity has already proven as a promising chemosensitization strategy to increase therapeutic response in cancer." (PMID 32456134, 2020).